PSMB7 (proteasome 20S subunit beta 7)
Description:
Component of the 20S core proteasome complex involved in the proteolytic degradation of most intracellular proteins. This complex plays numerous essential roles within the cell by associating with different regulatory particles. Associated with two 19S regulatory particles, forms the 26S proteasome and thus participates in the ATP-dependent degradation of ubiquitinated proteins. The 26S proteasome plays a key role in the maintenance of protein homeostasis by removing misfolded or damaged proteins that could impair cellular functions, and by removing proteins whose functions are no longer required. Associated with the PA200 or PA28, the 20S proteasome mediates ubiquitin-independent protein degradation. This type of proteolysis is required in several pathways including spermatogenesis (20S-PA200 complex) or generation of a subset of MHC class I-presented antigenic peptides (20S-PA28 complex). Within the 20S core complex, PSMB7 displays a trypsin-like activity.
Synonyms: Z
Tractability: Small molecule: an approved drug acts on it; a structure with a bound ligand is known; a high-quality ligand is known; it belongs to a druggable protein family. Antibody: its Gene Ontology location is reachable by antibodies, with high confidence. PROTAC: ubiquitination databases record sites on it; its protein half-life has been measured; a small molecule that binds it is known.
Target class: Threonine protease; Protease; Threonine protease T1A subfamily; Threonine protease PBT clan; Enzyme
Gene: Protein-coding gene on chromosome 9 (124,352,999 to 124,415,476, reverse strand). Ensembl gene ENSG00000136930.
Subcellular location: Cytoplasm; Nucleus
Subcellular location (Human Protein Atlas): Nucleoplasm; Cytosol; Nuclear bodies; Primary cilium
Pathways (Reactome):
Immune System: AMPK-induced ERAD and lysosome mediated degradation of PD-L1(CD274); Activation of NF-kappaB in B cells; Antigen processing: Ub, ATP-independent proteasomal degradation; Antigen processing: Ubiquitination & Proteasome degradation; CLEC7A (Dectin-1) signaling; Cross-presentation of soluble exogenous antigens (endosomes); Dectin-1 mediated noncanonical NF-kB signaling; Downstream TCR signaling; ER-Phagosome pathway; FCERI mediated NF-kB activation; GSK3B-mediated proteasomal degradation of PD-L1(CD274); Interleukin-1 signaling; NIK-->noncanonical NF-kB signaling; Neutrophil degranulation; SPOP-mediated proteasomal degradation of PD-L1(CD274); TNFR2 non-canonical NF-kB pathway
Cell Cycle: APC/C:Cdc20 mediated degradation of Securin; APC/C:Cdh1 mediated degradation of Cdc20 and other APC/C:Cdh1 targeted proteins in late mitosis/early G1; Autodegradation of Cdh1 by Cdh1:APC/C; Autodegradation of the E3 ubiquitin ligase COP1; Cdc20:Phospho-APC/C mediated degradation of Cyclin A; FBXL7 down-regulates AURKA during mitotic entry and in early mitosis; G2/M Checkpoints; SCF(Skp2)-mediated degradation of p27/p21; SCF-beta-TrCP mediated degradation of Emi1; Separation of Sister Chromatids; The role of GTSE1 in G2/M progression after G2 checkpoint; Ubiquitin-Mediated Degradation of Phosphorylated Cdc25A; Ubiquitin-dependent degradation of Cyclin D
Signal Transduction: Asymmetric localization of PCP proteins; Degradation of AXIN; Degradation of DVL; Degradation of GLI1 by the proteasome; Degradation of GLI2 by the proteasome; Degradation of beta-catenin by the destruction complex; GLI3 is processed to GLI3R by the proteasome; Hedgehog 'on' state; Hedgehog ligand biogenesis; MAPK6/MAPK4 signaling; Negative regulation of NOTCH4 signaling
and 29 more pathways
Gene Ontology:
Molecular function: protein binding; threonine-type endopeptidase activity; endopeptidase activity
Biological process: proteasomal protein catabolic process; proteasome-mediated ubiquitin-dependent protein catabolic process; regulation of proteasomal protein catabolic process; response to oxidative stress; apoptotic process; cellular response to type I interferon; DNA damage response; DNA repair; flagellated sperm motility; meiotic cell cycle; proteasomal ubiquitin-independent protein catabolic process; regulation of G1/S transition of mitotic cell cycle; spermatogenesis; protein catabolic process
Cellular component: cytoplasm; cytosol; nuclear body; nucleoplasm; nucleus; proteasome complex; proteasome core complex; extracellular region; ficolin-1-rich granule lumen; proteasome core complex, beta-subunit complex; proteasome storage granule; secretory granule lumen; spermatoproteasome complex; synaptic vesicle
Genetic constraint (gnomAD): Loss-of-function variants: 4 observed, 21.44 expected, observed/expected ratio (o/e) 0.19, 90% interval 0.091 to 0.43. The upper end of that interval is the gene's LOEUF score, 0.43, which puts it in group 1 of 6, group 1 being the genes least tolerant of losing a copy. Missense variants: 237 observed, 293.85 expected, observed/expected ratio (o/e) 0.81, 90% interval 0.73 to 0.9. Synonymous variants: 108 observed, 109.3 expected, observed/expected ratio (o/e) 0.99, 90% interval 0.85 to 1.16.
Homologues: Orthologues: chimpanzee PSMB7 (99% identical), macaque PSMB7 (99% identical), mouse Psmb7 (96% identical), dog PSMB7 (96% identical), guinea pig PSMB7 (95% identical), pig PSMB7 (95% identical), rat Psmb7 (95% identical), rabbit PSMB7 (91% identical), zebrafish psmb7 (79% identical), tropical clawed frog psmb7 (77% identical), Drosophila melanogaster Prosbeta1 (22% identical), Caenorhabditis elegans pbs-1 (19% identical). Paralogues in human: PSMB10 (57% identical), PSMB6 (26% identical), PSMB11 (24% identical), PSMB9 (23% identical), PSMB8 (21% identical), PSMB5 (20% identical), PSMA1 (18% identical), PSMA5 (18% identical), PSMA4 (18% identical), PSMA6 (18% identical), PSMA8 (17% identical), PSMB1 (17% identical), and 6 more.
Diseases named in the same sentence as PSMB7 in open-access papers:
PSMB7 is named in the same sentence as 45 diseases in open-access papers, as found by Europe PMC text mining. Sharing a sentence is not in itself a finding about the gene and the disease. The quoted sentences say what the papers report.
breast carcinoma (15 papers, 2010 to 2024). "Studies have found that in microarray samples of 1592 breast cancer patients, PSMB7 (gene encoded β5) has been found to be overexpressed in breast cancer cells and associated with poor prognosis." (PMID 38523673, 2024). "Another study demonstrated that PSMB7 is an unfavorable prognostic marker for breast cancer and is associated with anthracycline resistance." (PMID 36761753, 2023). "Furthermore, PSMB7 has been proved to be associated with anthracycline-resistance in breast cancer." (PMID 23762443, 2013). "Research links PSMB7 overexpression to tumour progression, drug resistance in multiple myeloma and shorter survival in breast cancer, underscoring its potential as a marker for cancer severity and treatment response." (PMID 38946232, 2024). "Similar to PSMB5, PSMB7 was found to contribute to anthracycline resistance and was predictive of significantly shorter survival in breast cancer." (PMID 35693739, 2022). "High expression of PSMB7 indicates the shorter survival of breast cancer patients; therefore, PSMB7 expression can serve as a poor prognostic marker in the disease." (PMID 29685151, 2018). "Conversely, high expression of proteasome subunits PSMB7 and PSMB4 has been shown to be associated with decreased breast cancer patient survival and poor prognosis, respectively." (PMID 26930717, 2016). "In our study we examined the function of the proteasome subunit PSMB7 gene in drug resistance in breast cancer cell line and in breast cancer patients." (PMID 20010949, 2010). "We grouped the 1592 breast cancer patients on the basis of the expression of PSMB7 using the Affymetrix HGU133A probe set 200786_at." (PMID 20010949, 2010). "Our findings suggest that high PSMB7 expression is an unfavourable prognostic marker in breast cancer." (PMID 20010949, 2010). "However, mutation events in PSM genes were relatively rare in cancer, which was also observed in the breast cancer validation dataset where only four PSM genes (PSMA4, PSMB7, PSMD3, and PSME4) harbored mutations." (PMID 36123629, 2022). "PSMB7 was identified to be a prognostic biomarker in breast cancer." (PMID 25936657, 2015). "High PSMB7 expression is an unfavourable prognostic marker in breast cancer." (PMID 20010949, 2010). "We also confirmed via qRT-PCR that proteasome subunit genes, such as PSMB7 and PSMD12, which are induced by NRF1 when the proteasome is inhibited, had attenuated expression in the NRF1-knockdown breast cancer cell lines." (PMID 37739987, 2023).
multiple myeloma (5 papers, 2021 to 2024). "Although the roles of PSMC gene mutations in cancer remain unstudied, multiple mutations in other proteasome family genes, i.e., PSMB5, PSMB6, and PSMB7, are associated with the myeloma cell survival." (PMID 35938038, 2022).
hepatocellular carcinoma (4 papers, 2012 to 2022). A malignant tumor that arises from hepatocytes. "Furthermore, down-regulation of PSMB7 enhanced hepatocellular carcinoma to 5-fluorouracil sensitivity." (PMID 35652069, 2022). "Aberrant expression of members of the proteasome subunit beta (PSMB) family (including PSMB2, PSMB4, PSMB7 and PSMB8) has been reported in hepatocellular carcinoma (HCC)." (PMID 36062301, 2022).
COVID-19 (2 papers, 2022 to 2024). A disease caused by infection with severe acute respiratory syndrome coronavirus 2. "Interestingly, PSMB5, PSMB6, and PSMB7 also did not reveal a significant difference between COVID-19 patients and HC, suggesting an overexpression of the immunoproteasome rather than constitutive proteasome." (PMID 35327634, 2022).
bipolar disorder (1 paper, 2018). A disorder of the brain that causes unusual shifts in mood, energy, activity levels and the ability to carry out day-to-day tasks. "PSMB7 has been shown previously to be associated with cell proliferation, the molecular mechanism of bipolar disorder, autophagy, and cancer." (PMID 30442960, 2018).
myeloid leukemia (1 paper, 2017). A clonal proliferation of myeloid cells and their precursors in the bone marrow, peripheral blood, and spleen. "However, the PSMB7 gene coding for β2 subunit is overexpressed in a large variety of solid cancers and myeloid leukemias." (PMID 28797244, 2017).
osteosarcoma (1 paper, 2025). A usually aggressive malignant bone-forming mesenchymal neoplasm, predominantly affecting adolescents and young adults.
pheochromocytoma (1 paper, 2025). "Then, we constructed amino acid metabolism profiles by WGCNA and LASSO regression model for investigating the impact of amino acid metabolism on pheochromocytoma pathogenesis and immunity and identified six hub genes (DDC, SYT11, GCLM, PSMB7, TYRO3, and AGMAT)." (PMID 38526709, 2025).
thymoma (1 paper, 2022). A neoplasm arising from the epithelial cells of the thymus. "Among the 33 cancer types, ACSL4 expression was most correlated with TMB in ACC, whereas FANCD2, HIF3A, HSPA5, and PSMB7 were most correlated with TMB in thymoma (THYM)." (PMID 35652069, 2022).
thyroid cancer (1 paper, 2023). "In a real-world experiment, the RT-qPCR results were consistent with the bioinformatic analysis, confirming that ADAMTSL4, DOCK6, FAM111B, and SEMA6B were expressed at higher levels in thyroid cancer cells (p < 0.05), while MRPS10 and PSMB7 were expressed at lower levels (p < 0.05)." (PMID 36761753, 2023).
tumor (18 papers, 2018 to 2025). "Studies suggest that the overexpression of PSMB7 in certain tumours might be associated with tumour proliferation, invasion and metastasis." (PMID 38946232, 2024). "Another prevalent fusion PSMB7::SCAI (52 tumor cells) detected mostly by long reads and with four fusion splicing isoforms involves suppressor of cancer cell invasion gene SCAI." (PMID 38464114, 2024). "Next, dual inhibition of PSMB5 and PSMB7 were performed in tumor cells using a combination of each specific siRNA at a suboptimal dose." (PMID 29515784, 2018). "In addition to exhibiting significantly lower expression levels in tumor cells, PSMB7 actively participates in the generation of MHC Class I-presenting antigen peptides by forming the 20S-PA28 complex." (PMID 38526709, 2025). "Transwell assays also demonstrated that PSMB7 knockdown inhibited tumour migration." (PMID 38946232, 2024). "Compared with the normal group, the expression of DDC and SYT11 were remarkably up-regulated in the tumor group, while the expression of GCLM, PSMB7, TYRO3, and AGMAT were remarkably down-regulated in the tumor group." (PMID 38526709, 2025). "Interestingly, by comparing the expression profiles of adriamycin resistance in four different pairs of human tumor cell lines, PSMB7 overexpression could be found in the drug-resistant cell lines, and the resistance of the cells was weakened after PSMB7 was silenced by RNA interference." (PMID 38523673, 2024). "Subsequently, utilizing machine learning techniques, we constructed the PIS model, comprising marker genes of CKS1B+ tumours (RHOV, ANLN, DEAR, PSMB7, KRT8, LDHA)." (PMID 38946232, 2024). "The validation part demonstrated that ADAMTSL4, DOCK6, FAM111B, and SEMA6B were expressed at higher levels in the tumor tissue, whereas lower expression of MRPS10 and PSMB7 was observed." (PMID 36761753, 2023). "Analysis of thousands of tumor samples from The Cancer Genome Atlas (TCGA) reported an increased expression of proteasomes such as PSMB6, PSMB7, and PSMD2 in most cancer types." (PMID 31877708, 2019). "In the analysis of gene expression in whole proteasomes including PSMB5 (β5), PSMB8 (iβ5), PSMB7 (β2), PSMB10 (iβ2), PSMB6 (β1), and PSMB9 (iβ1), these genes alternated or showed only slight in their expression following silencing of PSMB5 or PSMB7 in three tumor cells." (PMID 29515784, 2018).
cancer (17 papers, 2010 to 2025). A tumor composed of atypical neoplastic, often pleomorphic cells that invade other tissues. "We further explored the effect of 5 hub genes (ACSL4, FANCD2, HIF3A, HSPA5, and PSMB7) in 33 kinds of cancer in the TCGA database." (PMID 35652069, 2022). "The function of one of the catalytic subunits, the PSMB7 gene in cancer is still an undiscovered spot of molecular biology." (PMID 20010949, 2010). "In comparison to other cancer types, STS showed high expression of PSMB5, PSMB6 and PSMB7, the subunits of the constitutive proteasome and low levels of PSMB8, PSMB9 and PSMB10, the subunits specific to immunoproteasomes." (PMID 32851475, 2021). "A survey of public available data bases (COSMIC, canSAR, Cancer Cell Line Ecyclopedia) indicated that PSMB5 and PSMB7 genes are not mutated, deleted nor amplified in REC1 cells." (PMID 28797244, 2017). "Based on transcriptomic analyses of thousands of samples from The Cancer Genome Atlas, we report that expression of constitutive proteasome (CP) genes (PSMB5, PSMB6, PSMB7) and immunoproteasome (IP) genes (PSMB8, PSMB9, PSMB10) is increased in most cancer types." (PMID 27659694, 2016).
infection (5 papers, 2019 to 2024). The state of being infected such as from the introduction of a foreign agent such as serum, vaccine, antigenic substance or organism. "Interestingly, one protein that appearsreduced upon infection(over 3-fold change) in patients infected by SARS-CoV-2 is the proteasomesubunit beta-type 7 (PSMB7)." (PMID 39392878, 2024).
neurodegenerative disease (1 paper, 2011). A disorder of the central nervous system characterized by gradual and progressive loss of neural tissue and neurologic function. "Association of PDIA5 and BIRC6 (as well as PSMB7 and CYP1B1 in the Salt Lake City population) with POAG indicates that adult-onset glaucoma belongs to the same category of late onset neurodegenerative diseases." (PMID 21655191, 2011).
PSMB7 also shares sentences with these, for which no sentence is quoted: virus infection (4 papers); colorectal cancer (3); melanoma (3); Anxiety (1); arenavirus infection (1); bladder cancer (1); cannabis dependence (1); Cholestatic liver disease (1); Cirrhosis (1); colon cancer (1); dementia (1); depression (1); gastric carcinoma (1); glioblastoma (1); heart failure (1); Hepatitis (1); Hypertension (1); hypothyroidism (1); Lassa fever (1); liver disease (1); lung adenocarcinoma (1); malaria (1); mitochondrial disease (1); myofibrillar myopathy (1); myopathies (1); neurodevelopmental disorder (1); Non-alcoholic fatty liver disease (1); parasite infection (1); prostate carcinoma (1); serous ovarian cancer (1).
A further 1 disease shares a sentence with PSMB7 in 1 paper.